STAT3 (signal transducer and activator of transcription 3)
Diseases named in the same sentence as STAT3 in open-access papers (continued):
Sharing a sentence is not in itself a finding about the gene and the disease.
tumor (continued). "However, and unexpectedly, the identified variants included protein-truncating mutations, frameshift indels, and essential splice site mutations, indicating that JAK2 and STAT3 functions were lost upon mutation, thus suggesting they were operating as tumor suppressor genes in that setting." (PMID 30231553, 2018). "Sustained overproduction of IL-6 and STAT3 was found to contributes to arsenic causes carcinogenesis and STAT3 is also required for cellular transformation and performed pro-tumorigenic functions, including promotion of tumor cell proliferation, survival, invasion, metastasis, and angiogenesis." (PMID 30185897, 2018). "The anti-intestinal inflammation and anti-STAT3 properties of Hst would contribute its broad benefits to the management of diarrhea caused by other chemo or targeted agents, and more importantly, enhance and reinforce the anti-tumor effects of these agents, to improve patient outcomes." (PMID 29963254, 2018). "Multivariate analysis revealed that high STAT3 expression in the nucleus was significantly associated with cancer-specific survival after adjustment for pathological stage, lymph node involvement, lymphovascular invasion, and tumor grade (HR = 2.136, 95% CI = 1.009–4.767, p = 0.047)." (PMID 30091994, 2018). "One used the T3SS to deliver the tumour-associated antigen survivin, the other was programmed to lyse inside tumour cells, delivering a short-hairpin RNA targeted to knock down the tolerogenic gene Stat3, which normally drives expression of immunosuppressive molecules." (PMID 28382885, 2017). "A recent study suggested that STAT3 supports the expression of a drug-metabolizing enzyme and certain components of tumor-associated matrix that contribute to poor drug efficacy and delivery, therefore might also contribute to resistance to cytotoxic chemotherapy reported in PDAC." (PMID 28388589, 2017). "However, pharmacological inhibition of STAT3 did not completely abrogate GRIM-19 loss-driven tumorigenesis, suggesting that the full capacity of GRIM-19 loss to tumor growth may extend beyond its ability to activate STAT3." (PMID 27167343, 2016). "However, monoclonal antibodies targeting VEGF and EGFR may be un-sufficient to controlling the activity of other signaling pathways such as IL6/STAT3 signaling, which may exemplify the underlying mechanism of anti-tumor resistance." (PMID 27729020, 2016). "Also, increased macrophage infiltration and tumor microvascular density have been noted in tumors from ES patients with poor prognoses and tumor associated macrophages are known to express high concentrations of cytokines that lead to aberrant activation of the JAK/STAT3 pathway." (PMID 27317769, 2016). "BRG1 loss function mutation has been found in several kinds of cancers, and our demonstration of the important role of the BRG1/STAT3/VEGFC in tumor-associated lymphangiogenesis might lead to the discovery of novel therapeutic targets to treat cancer with BRG1 loss of function." (PMID 27145366, 2016). "Overexpression of miR-22 in male tumor adjacent tissue was associated with downregulated ERα expression, potentially by attenuating the protective effect of estrogen and causing increased IL-1α expression and STAT3 and IL-1α involved in inflammation and stemness inducible of HCC progression." (PMID 26503703, 2015). "In RCC, apart from polarizing macrophages into an M2 phenotype, CSF-1 could also lead to the activation of signal transducer and activator of transcription-3 (Stat3) which promotes cell survival and proliferation as well as immune responses associated with tumor progression." (PMID 25886010, 2015). "Therefore, our results call for cautious use of anti-IL-6-STAT3 signalling blockers in the treatment of PCa as this may turn low-grade tumours into highly malignant cancers by loss of senescence controlled by the STAT3–ARF axis." (PMID 26198641, 2015).
tumor (continued). "Importantly, the persistent activation of STAT3 intrinsic to tumor cells is transmitted to stromal inflammatory cells in the tumor microenvironment through activation of cytokines, chemokines and growth factors, and associated receptors, which in turn activate STAT3 in stromal cells." (PMID 26501341, 2015). "Persistent STAT3 activation may be due to the loss of suppressors of cytokine signaling and protein tyrosine phosphatases expression, as well as to autocrine or paracrine inflammatory stimulation in the tumor microenvironment." (PMID 28031890, 2015). "Indeed, a myeloid cell-specific deficiency in NF-κB activity reduces tumor formation, while a myeloid cell-specific deficiency of STAT3 results in the spontaneous development of colitis triggered by the gut microflora and leads to an enhanced rate of tumor formation in inflamed regions." (PMID 24723924, 2014). "However, the role of HspB1 towards STAT3 is probably more complex than it has been originally thought since, depending upon the mutational background of the tumor, STAT3 can either be pro-oncogenic or have a tumor suppressor activity." (PMID 24514166, 2014). "Subsequently, a number of well-performed studies have suggested that the activation of STAT3 might not be uniformly associated with increased malignancy, and that in some circumstances STAT3 might act as a functional tumor suppressor or its activation may be associated with an improved prognosis." (PMID 24762632, 2014). "However, even though IL-6 seems to be associated with tumor progression, its relationship with the AR is convoluted and IL-6/STAT3 can have both pro and anti-proliferative effects on tumor cells as that depends on AR status of PCa cells well as activity/crosstalk from other pathways." (PMID 24722453, 2014). "Thus, whether STAT3 behaves as a tumor suppressor or oncogene relies on the tumor genetic background—activation of STAT3 in PTEN deficient GBM may actually prevent tumor invasion and stabilize tumor growth." (PMID 24518612, 2014). "While, we believe that chronic IL-6 expression may be responsible for STAT3 and NFκB downregulation in tumor associated inflammatory cells; its systemic effect may be stimulatory, due to lower concentration in the body compared to the intratumoral concentration." (PMID 25400927, 2014). "A recent studies showed that Stat3 is frequently activated not only in diverse cancer cells by common oncogenic pathways, but also in tumor endothelial and myeloid cells, including Gr1+/CD11b+ (MDSCs) and tumor-associated macrophages, mediating immune suppression." (PMID 24416452, 2014). "Furthermore, STAT3 activation by conditioned medium of tumor-associated fibroblasts could be blocked by berberine or antibodies against IL-6 and IL-6R." (PMID 24380387, 2013). "Besides, berberine could abrogate the activation of STAT3 in NPC cells induced by the IL-6 secreted from tumor-associated fibroblasts." (PMID 24380387, 2013). "In addition, tumor size also exhibited significant association with STAT3 expression (P = 0.003)." (PMID 21575192, 2011). "Similarly, the membrane-associated Hsp72 on tumor-derived exosomes was reported to mediate STAT3-dependent immunosuppressive function of MDSCs by triggering STAT3 activation in a Toll-like receptor- (TLR-) 2/MyD88-dependent manner, although the role of TLR2 in this process remains controversial." (PMID 22190973, 2011). "Therefore, the association of STAT3 activation with tumor progression suggests that STAT3 may be an attractive molecular target for cancer therapy." (PMID 17683579, 2007).
tumor (continued). "Western blot analysis of tumor tissues revealed significant inhibition of STAT3 and AKT phosphorylation, as well as downregulation of c-Myc expression, in the combination group." (PMID 41539998, 2026). "In preclinical studies, this mutant exert gain‐of‐functions through constitutively binding to and hyperactivating STAT3, leading to increased proliferation and aggressiveness of tumor cells." (PMID 41498535, 2026). "Mechanistically, both in vitro and in vivo data showed that MrEVs activate the Janus kinase 2/signal transducer and activator of transcription 3 (JAK2/STAT3) signalling pathway, thereby driving M2 polarisation and tumour malignancy." (PMID 42249590, 2026). "Inhibition of JAK/STAT3 selectively inhibited the growth of ARID1A deficient endometria cancer cells in vitro and in a mouse xenograft tumor model." (PMID 41800254, 2026). "IL-6 can also activate the JAK/STAT3 signaling pathway, which in turn promotes the expression of genes that are involved in immune evasion, metastasis, and tumor cell survival." (PMID 41497141, 2026). "TN-induced PTGS2 downregulation leads to the inhibition of the JAK/STAT3/c-Myc signaling axis, resulting in suppression of tumor proliferation and the induction of autophagic cell death." (PMID 41800258, 2026). "In light of our findings and the published literature, we postulated that the activation of STAT3 serves as a “self-protective” mechanism employed by tumor cells to counteract inhibition of the EGFR/MEK/ERK pathway." (PMID 41539998, 2026). "In contrast, the loss of STAT3 signaling facilitates escape from dormancy, downregulates LIFR expression, and promotes tumor proliferation and colonization." (PMID 41596432, 2026). "In tumor cells, STAT3 promotes stemness, survival, checkpoint ligand expression, impaired antigen presentation, and immunosuppressive secretomes." (PMID 42238578, 2026). "Conversely, PGD2 has shown tumor-suppressive effects by activating PPAR-γ, limiting tumor self-renewal, growth, and metastasis through inhibition of STAT3 signaling." (PMID 41596686, 2026). "Through GABA secretion, tumor cells suppress the NF‐κB and STAT3 pathways, inhibiting M1 polarization and promoting M2 phenotype development via STAT6 activation, thus suppressing antitumor immunity." (PMID 41583906, 2026). "The results indicate that Astragaloside IV exerts a potent dual inhibitory effect on STAT3 and NF-κB in tumor cells MB-49, thereby inhibiting tumor angiogenesis." (PMID 41596251, 2026). "The IL-6 and IL-23 receptors signal through signal transducer and activator of transcription 3 (STAT3) in the tumor microenvironment." (PMID 41749853, 2026). "It has been established that SDF-1α, through its receptor CXCR4, activates critical signaling pathways (PI3K/Akt, MAPK/ERK, JAK/STAT3) that promote tumor growth, invasion and migration." (PMID 41597220, 2026). "In turn, we identified STAT3 as a palmitate responsive regulator of KAT2A expression in tumor spheroids and lung metastases." (PMID 41826695, 2026). "We show that extracellular S100-A11 promotes tumour cell proliferation and is associated with activation of the RAGE/STAT3 signalling axis." (PMID 42155177, 2026). "Mechanistically, tumor-derived SERPINE1 drives TAM M2 polarization through the let-7g-5p/SOCS7/STAT3 axis, promoting GC progression and therapeutic resistance." (PMID 41601623, 2026). "Lung injury, inflammation, thrombosis, fibrosis, STAT3 activation, cytokine profiles, and tumor burden were assessed." (PMID 41988188, 2026). "They activate the CSF1/CSF1R and IL‐10/STAT3 pathways, induce T‐cell exhaustion and metastatic phenotype switching, promote tumor infiltration and metastasis, and substantially shorten disease‐free and overall survival." (PMID 41426206, 2026). "This promotes YTHDF1-dependent translation, JAK1 upregulation, and downstream STAT3 activation, thereby reinforcing the immunosuppressive phenotype of tumor-infiltrating myeloid cells (TIMs) and promoting immune evasion." (PMID 41491598, 2026).
tumor (continued). "In our experiments, LyECs exhibited significant increases in IL-6 secretion and STAT3 activation, both of which are known to promote lymphangiogenesis and tumor progression." (PMID 41583514, 2026). "This inhibitor binds specifically to the SH2 domain of STAT3, suppressing tumor growth, metastasis, and remodeling the tumor microenvironment." (PMID 41596231, 2026). "For instance, ADs weaken CSC properties by inhibiting the AKT/mTOR signaling axis, restore apoptosis sensitivity through modulation of the Bcl-2/Bax balance, and alleviate tumor-induced immunosuppression by blocking STAT3 signaling." (PMID 41599293, 2026). "In HCC, TAMs play a critical role in sustaining an immunosuppressive microenvironment and facilitating tumor progression via STAT3 activation." (PMID 41426206, 2026). "Elevated IL-6 levels in the bone microenvironment further potentiate STAT3 activation, contributing to tumor survival and dormancy." (PMID 41596432, 2026). "NF-κB and STAT3 pathways crosstalk with enhance the production of pro-inflammatory cytokines like IL-6, which create a tumour permissive microenvironment." (PMID 41476776, 2026). "GMI inhibited STAT3, reduced macrophage M2 polarization and SIRPα levels and enhanced their immune and anti-tumour functions." (PMID 41438583, 2026). "Stattic effectively suppressed STAT3 phosphorylation and reduced both the number and size of tumor spheres formed." (PMID 41438576, 2026). "It mainly acts as an inhibitor of cellular processes by regulating transcription factors NF-κB and JAK/STAT3 in tumor cells." (PMID 41596531, 2026). "Targeting oncogenic signaling pathways, Lactobacillus rhamnosus and B. pseudolongum inhibit IL-6/STAT3 pathway activity by reducing IL-6 levels or enhancing STAT3 methylation, respectively, and thus blocking tumor cell growth and angiogenesis." (PMID 40990659, 2026). "Our findings identify MFN2 as a critical suppressor of tumor immune evasion through the EGFR/STAT3-PD-L1 signaling pathway." (PMID 41896539, 2026). "Specifically, we explore broad mechanisms of immune evasion, including STAT3-PD-L1 regulation, modulation of innate immune surveillance, T cell exhaustion, and remodeling of stromal and fibrotic tumor niches." (PMID 42266182, 2026). "Immune processes included IL6/JAK/STAT3 signaling, Type I and II Interferon Responses, Toll-like Receptor signaling, and T cell receptor signaling, highlighting a more immunoreactive tumor microenvironment." (PMID 41493679, 2026). "Our data establish NBL1 as a critical driver of OC metastasis through dual mechanisms: i) direct activation of Jak/Stat3 signaling via physical interaction, and ii) suppression of anti-tumor immunity by limiting T cell infiltration." (PMID 41158754, 2026). "In this model, SDF-1 and HGF promote the recruitment and activation of stromal cells, while LIF and, possibly, SCGF-β directly target tumor cells by activating key oncogenic signaling pathways such as JAK/STAT3 and PI3K/Akt." (PMID 41597220, 2026). "This direct interaction effectively suppresses STAT3 phosphorylation and nuclear translocation, leading to inhibition of tumor proliferation, migration, and EMT." (PMID 41601649, 2026). "EATL is characterized by strong inflammatory activity, with enriched gene sets like interferon response and IL-6/JAK/STAT3 signaling and overexpressed inflammation-related genes (e.g., PD-L1, CXCL13), suggesting STAT3-driven tumor-promoting inflammation." (PMID 41057685, 2026). "In ovarian cancer, embryonic TAMs expressing CD163 and T‐cell immunoglobulin and mucin‐domain containing molecule 4 (Tim4) produce high levels of IL‐6 and erythropoietin, activating STAT3 to promote tumor progression and invasion." (PMID 41426206, 2026).
tumor (continued). "Protein expression of BUB1, STAT3, and p-STAT3 in tumor tissues was further analyzed by Western blot and immunohistochemistry (IHC)." (PMID 42164122, 2026). "One of the major activators of STAT3 signaling in M-MDSCs is IL-617, an abundant cytokine in the TME released by tumor cells, stromal cells such as fibroblasts, tumor-associated macrophages, and tumor-infiltrating M-MDSCs19." (PMID 41535266, 2026). "For example, PTEN and CASP8 act as tumor suppressors, whereas STAT3, MYC, EGFR, and TGFB1 are canonical oncogenic drivers implicated in cell cycle progression, stemness, and therapy resistance, particularly in triple-negative BC." (PMID 41596512, 2026). "CPA-7 was tested in vitro for its ability to inhibit STAT3 signaling, alter proliferation, and cause cell death in HPV16+ C3.43 tumor cells." (PMID 41749853, 2026). "Here, we discuss how STAT3 functions at the tumor-immune interface to coordinate immune escape and highlight therapeutic opportunities for targeting this axis in cancer." (PMID 42238578, 2026). "Mechanistically, FCGBP modulated the PIGR/JAK2/STAT3 signaling pathway, thereby exerting both anti-tumor and anti-CDDP resistance effects." (PMID 41560312, 2026). "Concurrently, E7 promotes activation of the STAT3, a transcription factor involved in immune suppression and tumor promotion." (PMID 41497141, 2026). "STAT3 is a key signaling pathway involved in the progression and modulation of the tumor microenvironment across multiple cancer types." (PMID 41560805, 2026). "The immune processes included IL6/JAK/STAT3 signaling, Type I and II Interferon Responses, Toll-like Receptor signaling, and T cell receptor signaling, highlighting a more immunoreactive tumor microenvironment." (PMID 41493679, 2026). "STAT3 activation influences genes that modulate the survival, proliferation, angiogenesis, invasion, and immune evasion of tumor cells to varying extents." (PMID 41158754, 2026). "These metabolites regulate essential oncogenic and inflammatory pathways, including Wnt/β-catenin, NF-κB, and STAT3, and alter the tumor microenvironment by affecting regulatory T cells (Tregs), Th17 cells, macrophages, and myeloid-derived suppressor cells." (PMID 42292406, 2026). "NF-κB and STAT3 are two key factors that help pre-neoplastic and malignant cells resist apoptosis-driven tumor surveillance and manage tumor angiogenesis and invasiveness." (PMID 41596531, 2026). "Together, E6- and E7-mediated dysregulation of NF-κB and STAT3 not only drives persistent inflammation but also enables the virus to subvert host immunity, creating favorable conditions for tumor initiation and progression." (PMID 41497141, 2026). "The downregulation of MCPIP1 expression promotes a tumor-promoting microenvironment through the coordinated activation of the β-catenin, STAT3, and CREB1 pathways." (PMID 41955682, 2026). "reuteri mutant or blocking host STAT3 lactylation using STAT3-knockout cells reconstituted with wild-type STAT3 or lactylation-defective STAT3 K631R, abolished the pro-tumor and antiferroptotic effects in vitro and in vivo." (PMID 42281240, 2026). "Activation of STAT3 and upstream cytokines such as IL-6 promotes tumor cell survival, stromal remodeling, and resistance to 5-fluorouracil (5-FU) and oxaliplatin through modulation of EMT, DNA repair pathways, and anti-apoptotic programs." (PMID 41516350, 2026). "The resulting humanized antibodies, huE17 and huNA7, exhibited target specificity and effectively inhibited IL-6 induced STAT3 activation and tumour promoting phenotypes in vitro." (PMID 42316398, 2026). "This protein can be ingested by macrophages and promotes fatty acid peroxidation via a STAT3‐mediated mechanism inside the cell, inducing macrophage differentiation into the M2 type and facilitating tumor immune evasion." (PMID 41560416, 2026). "Phosphorylated STAT3 expression correlates positively with tumor invasion depth in human SCC and basal cell carcinoma specimens compared with normal skin." (PMID 41596287, 2026).